TNF (tumor necrosis factor)
Diseases named in the same sentence as TNF in open-access papers (continued):
Sharing a sentence is not in itself a finding about the gene and the disease.
glioma (continued). "Since EMT and TNF-α were found to be highly involved in the progression of glioma, the increased level of LINC00941 and the decreased level of BASP1-AS1 might account for the promoted proliferation of glioma cells through activating EMT and TNF-α signaling pathway." (PMID 34659218, 2021). "Hyperbaric oxygen therapy (HBOT) could inhibit glioma cell proliferation and inflammatory cell infiltration, and exert a sensitizing effect on ACNU therapy partially through enhancing oxygen pressure (PO2) in tumor tissues and lower expression levels of HIF‐1α, TNF‐α, IL‐1β, VEGF, MMP9, and NF‐κB." (PMID 27734611, 2016). "RNA-seq and qPCR analyses also verified that TWEAK but not TNFα treatment elevated NIK transcription, which was also observed in actively invading glioma cells." (PMID 36945490, 2023). "The results from RT-PCR demonstrated a notable upsurge in the expression of two M1 macrophage markers—TNF-α and IL-6—in non-GBM gliomas." (PMID 38283752, 2023). "Further qRT-PCR analysis revealed that in the presence of glioma cells, WT but not CD44-/- microglia notably increased mRNA levels of TNF-α." (PMID 35992852, 2022). "TNF‐α treatment elevated proliferation activity through NF‐κB signalling in normal glioma cells, but not in TNIP1‐down‐regulated glioma cells." (PMID 31691497, 2020). "Flow cytometry analysis revealed that treatment of glioma cells with recombinant type I IFN or infection with VSVΔ51, but not treatment with TNF-α, resulted in the increased surface expression of PD-L1 and major histocompatibility complex (MHC) I markers." (PMID 28198370, 2017). "However, the mRNA levels of M1 markers, TNF-α and IFN-γ were not statistically significant between HMC3 cells co-cultured with NC and shAEG-1 glioma cells groups." (PMID 34462446, 2021). "Considering malignant glioma cells and HCT8 cells are both cancer cells, we suppose that some factor(s) present in HPMECs but absent in cancer cells may compensate for the lack of HuR in regulating IL-8 but not ICAM-1 after TNF-α stimulation." (PMID 27215284, 2016).
uveitis (377 papers, 2009 to 2026). An inflammatory process affecting a part of or the entire uvea. "Research work indicates that uveitis is strongly associated with inflammatory and immune cytokines, including tumor necrosis factor, interleukin 1 (IL-1), IL-2, IL-6, IL-8, and interferon gamma (IFN-γ)." (PMID 40687721, 2025). "Among TNF-α inhibitors, etanercept was linked to a higher risk of new-onset and recurrent uveitis in AS patients than other similar biologics." (PMID 40621455, 2025). "For example, tumor necrosis factor (TNF)-alpha inhibitors are efficacious in the treatment of uveitis but are contraindicated in patients with MS due to the risk for worsening demyelination." (PMID 41239063, 2025). "Conversely, the APTITUDE trial enrolled 21 pediatric patients with anti-TNF-α refractory JIA-associated uveitis and found that only 33% met the resolution of ocular inflammation by week 12 after subcutaneous tocilizumab treatment." (PMID 41424786, 2025). "The lower risk of uveitis observed among patients receiving JAK inhibitors suggests potential mechanistic differences compared with TNF inhibitors." (PMID 41208989, 2025). "For uveitis, the pathogenesis is associated with the activation of Th1 and Th17 cells, which secrete inflammatory cytokines such as TNF-alpha, IL-17, IL-23, and IL-6, driving the inflammatory response." (PMID 40038580, 2025). "Various guidelines have been established for the use of TNFi in AS-associated AU; the American Academy of Ophthalmology (AAO) recommends TNF inhibitors as second-line immunomodulatory agents for severe uveitis associated with spondyloarthritis." (PMID 38337605, 2024). "The cytokine tumor necrosis factor-alpha (TNF-a), or TNF-A, is implicated in the pathogenesis of autoimmune ocular inflammatory diseases, including uveitis, in the context of inflammatory ocular conditions." (PMID 39407875, 2024). "Compared to anti-TNF-α monoclonal antibodies, etanercept demonstrates lower efficacy and offers weaker protection against the initial onset or recurrence of uveitis associated with JIA." (PMID 39062219, 2024). "A meta-analysis of 88 studies involving a cohort of 369 patients with Behçet’s disease treated with anti-TNF agents revealed that 89% (233/262) of the patients with Behçet’s disease-associated uveitis experienced sustained remission following IFX therapy." (PMID 39449328, 2024). "The well-known proinflammatory cytokines IL-1β, IL-6, IL-12, IL-23, IL-17, and TNFα have been implicated in the progression of various diseases, including type I diabetes, multiple sclerosis (MS), uveitis, and atherosclerosis." (PMID 38891990, 2024). "The most recent recommendations from the European League Against Rheumatism for the treatment of Behçets-associated uveitis, including retinal vasculitis, include anti-TNF-alpha therapies as first-line therapy." (PMID 37294447, 2023). "TNF-α-induced uveitis in rats is associated with IL-6; therefore, TNF-α and IL-6 inhibition in the AqH suppresses uveitis development." (PMID 36977246, 2023). "In the APTITUDE study, a multicenter phase 2 single-arm trial, 21 pediatric patients with JIA-associated uveitis previously refractory to methotrexate, and TNF-alpha inhibitors were treated with subcutaneous tocilizumab over six months." (PMID 36902105, 2023). "TNF-α production during the early phase of uveitis is associated with the mitochondrial oxidative stress of retinal cells." (PMID 37878302, 2023). "The recent ACR and SHARE guidance for management of JIA associated uveitis recommends addition of anti-TNF for control of JIA-associated uveitis, which is refractory to methotrexate." (PMID 36864437, 2023). "BD-associated uveitis is still a leading cause of blindness worldwide, although the treatment has undergone a paradigm shift with the introduction of tumor necrosis factor (TNF)-α inhibitors." (PMID 36744150, 2023).
uveitis (continued). "Tumor necrosis factor-α (TNF-α) has been associated with the immunopathogenesis of uveitis, herpetic stromal keratitis, and corneal response to injury." (PMID 37108070, 2023). "Intravenous tocilizumab is considered an option for children with anti-TNF refractory juvenile idiopathic arthritis-associated uveitis." (PMID 37700264, 2023). "Tumor necrosis factor inhibitors have been associated with the paradoxical onset or recurrence of uveitis or sarcoidosis, as well as optic neuritis, demyelinating optic neuropathy, chiasmopathy, and oculomotor palsy." (PMID 34802085, 2022). "Due to failure or loss of efficacy during anti-TNFα therapy, the use of abatacept or tocilizumab in two children was needed to achieve the uveitis’s control." (PMID 34669094, 2022). "The aim of the present study is to describe a cohort of children with severe uveitis and to highlight the risk factors for a pejorative development that led to the prescription of anti-TNFα drugs." (PMID 35311049, 2022). "Interleukin-1 alpha, interleukin-1 beta, and tumor necrosis factor are shown to be associated with endotoxin-induced uveitis." (PMID 36157069, 2022). "In an animal model, Ech has been shown to reduce the intraocular inflammation caused by endotoxin-induced uveitis by reducing ROS production, as well as by reducing the expression of NF-kB and TNF-α." (PMID 36233004, 2022). "The proinflammatory factors TNF-α, IL-1β and IL-6 are also associated with the development of uveitis." (PMID 35625654, 2022). "DC- and macrophage-derived IL-1β, TNF-α, and IL-12 have the most important pathogenic roles in the development of uveitis." (PMID 36362313, 2022). "Positive ANA is also associated with anti-TNFα therapy [OR = 3.89 (1.07–14.11), p = 0.0391], and it is established that they are a risk factor of developing uveitis when having JIA." (PMID 35311049, 2022). "Persistent production of TNF-α occurs in many autoimmune inflammatory diseases, including uveitis, and this is associated with significant tissue damage." (PMID 36530572, 2022). "As far as clinical criterion is concerned, uveitis diagnosis under the age of 6 years increased the risk of anti-TNFα therapy in our study [OR = 4.05 (1.16–14.13), p = 0.0284]." (PMID 35311049, 2022). "HLA-DRB1*08 positivity is associated with higher levels of TNF-α in the aqueous humor of patients with active uveitis." (PMID 34394873, 2021). "As regards biologics, a recent review highlighted a variety of data associating the new onset of uveitis, as a paradoxical effect of anti-TNF therapy in rheumatic conditions, predominantly under etanercept." (PMID 33802255, 2021). "Infliximab, a tumor necrosis factor antagonist, can effectively treat vitreous opacity, active retinal vasculitis, and macular cystic edema caused by uveitis and scleral inflammation, but it can lead to tuberculosis and aggravate demyelination disease." (PMID 34778467, 2021). "An immune response to the agent employed is an important cause of LOR in the treatment of JIA-associated uveitis with anti-TNFα- antibodies." (PMID 34419092, 2021). "Two RCTs (trials SYCAMORE and ADJUVITE) confirmed clinical efficacy of anti-TNF-α antibody for uveitis associated with juvenile idiopathic arthritis (JIA), and they were also included in this study." (PMID 34527074, 2021). "IL-6, TNF-α, and IL-1β are also associated with dry eye, uveitis, proliferative diabetic retinopathy, and diabetic macular edema." (PMID 34285659, 2021). "In the adalimumab and infliximab group, children with JIA-associated uveitis should be viewed differently, as it has been suggested that a higher dosage of anti-TNF drug is needed for penetration to obtain adequate drug levels in the eye." (PMID 33926495, 2021). "Agents that enhance microtubule stabilization can also mitigate the destruction of the corneal endothelial cell barrier caused by TNF-α-induced inflammation in transplant rejection and uveitis." (PMID 34992695, 2021).
uveitis (continued). "Numerous reports demonstrate that TNF-α is a major NF-κB dependent inflammatory cytokine, which results in increased risk of ocular inflammatory disease, including uveitis and age-related macular degeneration." (PMID 34285659, 2021). "We found a variety of data associating new onset of uveitis with anti-TNF therapy for rheumatic conditions, predominantly under etanercept." (PMID 32337619, 2020). "The occurrence of uveitis in patients receiving an anti-TNF-α agent seems linked more to the history of uveitis than the prescribed molecule." (PMID 32336278, 2020). "During uveitis, elevated levels of cytokines such as TNFα or IL-17A cause disruption of RPE barrier properties." (PMID 32101556, 2020). "Our aim was to study the safety and efficacy of tocilizumab in children with juvenile idiopathic arthritis-associated uveitis refractory to both methotrexate and TNF inhibitors." (PMID 32280950, 2020). "When facing a case of uveitis related to anti-TNF-α, it is important to consider other etiologies associated with the use of these agents, since this type of therapy is associated with increased risk of infections, particularly granulomatous ones." (PMID 32337619, 2020). "We gathered mainly case reports and retrospective studies which, considering the broad spectrum of uveitis causes and its potential link to the underlying auto-immune diseases treated with anti-TNF-α, can lead to confounding errors." (PMID 32337619, 2020). "In this review, we found ample data associating new onset of uveitis with anti-TNF therapy for rheumatic conditions, predominantly in patients with spondyloarthritis and under etanercept." (PMID 32337619, 2020). "The overproduction of pro-inflammatory cytokines such as tumor necrosis factor (TNF)–α and interleukin (IL)–6 has been found to be associated with inflammatory attacks in uveitis." (PMID 31335861, 2019). "When children with moderate-severe uveitis are refractory to MTX, monoclonal anti-TNF agents have been trialled the results show that adalimumab in combination with methotrexate was effective at treating JIA-associated uveitis." (PMID 30886955, 2018). "One study used tocilizumab to treat JIA-associated uveitis refractory to immunosuppressive drugs and anti-TNF agents." (PMID 30547812, 2018). "This is a novel adaptive design study of subcutaneous IL-6 inhibition in anti-TNF refractory JIA associated uveitis which will be able to determine if further research should be conducted." (PMID 30886955, 2018). "This lack of change is surprising, as the diagnostic tools and treatment for uveitis have improved over this time period, particularly with the introduction of various novel treatment options such as anti-TNF drugs and other medications." (PMID 29164419, 2017). "IL-6 can be induced by cytokines such as IFN-γ, TNF-α and IL-1β, which is an important cytokine that causes inflammatory response of uveitis." (PMID 28384257, 2017). "Previous studies demonstrated that etanercept decreased intraocular inflammation in a rat model of uveitis and prevented retinal ganglion cell loss in a rat model of glaucoma by reducing the TNF-α level." (PMID 27259948, 2016). "Anti–TNF therapy was associated with less uveitis than placebo in patients with AS (OR: 0.35, 95% CI: 0.15–0.81, P = 0.01)." (PMID 25888248, 2015). "A French national surveillance and numerous English case reports highlighted the association between TNFα inhibitors and uveitis, with 31 and 121 cases, respectively." (PMID 24991219, 2014). "Patients who also have A allele in −238 and −308 nucleotides of the TNFα gene promoter are more prone to uveitis." (PMID 24991219, 2014). "Extensive evidence supports the efficacy of TNF-α antagonists in the treatment of uveitis associated with rheumatologic disease." (PMID 22229035, 2012).
uveitis (continued). "The infection of guinea pigs with the L. interrogans serovar Icterohemorrhagiae increased the levels of IL-6 and TNFα mRNA in the lungs, and uveitis of leptospiral origin was associated with an increased production of the cytokines IL-6 and IL-8." (PMID 23132959, 2012). "Biologic treatment of the uveitis associated with PsA, like the other seronegative spondyloarthropathies, centers on the anti-TNF-α therapies." (PMID 22229035, 2012). "A case report described successful treatment with anakinra for chronic infantile neurological cutaneous articular syndrome (CINCA)-associated uveitis, refractory to anti-TNF therapy." (PMID 22454752, 2011). "The recurrence of uveitis is often associated with elevated serum levels of TNF-α with significant changes in aqueous humor levels." (PMID 20806043, 2010). "However, initiating anti-TNF treatment in recalcitrant cases of uveitis of undetermined cause with a positive IGRA is problematic if ATT has not been initiated first, as the risk of active TB disease is significantly increased." (PMID 41018498, 2025). "Etanercept increased the risk of uveitis compared to other TNF-α inhibitors." (PMID 40621455, 2025). "TNFα and IL-6, characteristic proinflammatory cytokines, are thoroughly implicated in BD aggravation, as they are released by monocytes and T lymphocytes in patients with BD uveitis, and participate in the formation of BD lesions, such as ocular lesions." (PMID 39798064, 2025). "However, the implications of long-term TNF inhibitor therapy on the risk of uveitis after the initial short-term period remain uncertain." (PMID 38337605, 2024). "Whereas effective in the treatment of some forms of uveitis, current systemic TNFα antagonists are associated with significant safety issues, notably increased risks of serious infections, including tuberculosis, some types of malignancy, and demyelinating disorders." (PMID 35704329, 2022). "The aim of the present study is to describe a cohort of children with severe uveitis associated with inflammatory or idiopathic diseases and to highlight the risk factors for a pejorative development that led to the prescription of anti-TNFα drugs." (PMID 35311049, 2022). "Thomas found that TNF-α inhibitors such as Adalimumab and infliximab may be considered as first-line therapy for Uveitis associated with Behcet disease and juvenile idiopathic arthritis." (PMID 35280901, 2022). "In addition, Infliximab (IFX, anti-TNF drug) is approved in Japan for BD-associated uveitis, where it has demonstrated good tolerance and efficacy." (PMID 35806031, 2022). "Although most of the evidence is in JIA-associated uveitis, it is worth mentioning the use of Tocilizumab with success in non-infectious uveitis with macular oedema and in Behcet's disease as an alternative to anti-TNF agents." (PMID 35979409, 2022). "Some studies have suggested that the aqueous TNF-α level is associated with uveitis and glaucoma, but it is unclear whether this reflects DR severity." (PMID 35770197, 2022). "However, this network meta-analysis demonstrates that anti-TNF mAb are associated with a lower incidence of uveitis compared to placebo and anti-IL17A." (PMID 34271991, 2021). "Evidence suggests a marked association between TNF-α and uveitis." (PMID 34795583, 2021). "The activation of Th17 cells with Th17-related proinflammatory cytokine induction (IFN-γ, TNF-α, IL-1β, IL-6, IL-23) could result in spondyloarthritis with associated uveitis." (PMID 35087531, 2021). "Compared to the other anti-TNF-α, drugs etanercept had a higher association with uveitis." (PMID 32337619, 2020). "Tumor necrosis factor α (TNFα) is associated with the onset of uveitis." (PMID 32101556, 2020). "Anti-TNF-α agents treatment is a promising option for controlling BD-associated uveitis." (PMID 32670062, 2020). "Our results suggest that IL-10 polymorphisms may have a role in susceptibility to TIN/TINU while genetic variation in TNF-α gene may be connected to isolated uveitis." (PMID 30779760, 2019).